ACE (angiotensin I converting enzyme)
Diseases named in the same sentence as ACE in open-access papers (continued):
Sharing a sentence is not in itself a finding about the gene and the disease.
Hypertension (continued). "The importance of ACE in maintaining the BP can be observed via the beneficial effect of ACE inhibitors in treating hypertension." (PMID 23533459, 2013). "About 59% of aware diabetic individuals with known hypertension were being treated with ACE inhibitors or ARBs." (PMID 23637851, 2013). "It is well established that the use of ACE inhibitors in diabetes and hypertension leads to an improvement of proteinuria, renal function and the risk of death and dialysis." (PMID 23446441, 2013). "Again similar results were obtained as in the primary analyses, the only difference being that now also known hypertension and use of ACE inhibitors/ angiotensin receptor blockers were significant covariates." (PMID 23723966, 2013). "The data of the present study provide additional support for a role for the RAS in the control of energy balance and the potential for beneficial effects of ACE inhibitors as a therapeutic strategy for patients with obesity and concomitant hypertension." (PMID 23894285, 2013). "ACE has been recognized as critical in the renin-angiotensin-aldosterone system (RAAS) for leading to hypertension." (PMID 25969772, 2013). "ACE is an important component of the renin - angiotensin system and plays an important role in hypertension and other cardiovascular and cerebrovascular diseases." (PMID 24354906, 2013). "Attempts have been made to explore natural products as cure for hypertension including ACE inhibitory peptides." (PMID 24093919, 2013). "It has been shown that patients taking angiotensin converting enzyme (ACE) inhibitors for hypertension, occasionally suffer from pruritus as a side effect." (PMID 23497684, 2013). "For hypertension treatment, the inhibition of angiotensin converting enzyme (ACE) is a major modern therapeutic approach." (PMID 24371832, 2013). "Pharmacological blockage of the RAS is used to treat hypertension, diabetic nephropathy, and congestive heart failure, but antigen II receptor blockers (ARBs) and ACE inhibitors also suppress proinflammatory cytokines and reduce oxidative stress." (PMID 23437094, 2013). "Second, although anti-platelet agents and “Yiqi-Huoxue” Chinese herbal medicines were prohibited during the trial, other drugs including beta-blockers, ACE inhibitors, lipid-lowing drugs, and drugs for hypertension and diabetes were allowed." (PMID 23935677, 2013). "Hypertension control: angiotensin-converting enzyme (ACE) inhibitors or angiotensin receptor blockers are administered to the majority of patients due to additional benefits of these medications." (PMID 24351097, 2013). "According to these studies, the 90 kDa N-domain ACE was suggested as a genetic marker of hypertension." (PMID 22666552, 2012). "Angiotensin-converting enzyme (ACE) inhibitors are used primarily (in some cases as the first choice drugs) for the treatment of hypertension and congestive heart failure." (PMID 24250503, 2012). "The ACE inhibitor Enalapril abolished hypertension in both male and female IUGR offspring, indicating that the RAS is involved in the regulation of hypertension." (PMID 22319540, 2012). "Captopril is a common orally administered ACE inhibitor used to treat hypertension and congestive heart failure." (PMID 22853321, 2012). "Competitive inhibition of ACE is more frequently reported, including the common hypertension drugs, such as captopril, enalapril, and lisinopril; these drugs compete with the substrate for binding to the active site of ACE." (PMID 22606330, 2012). "Therenin-angiotensin system (RAS) is a criticalregulator of hypertension, primarily through theactions of the vasoactive peptide Ang II, whichis generated by the action of angiotensin-converting enzyme (ACE) mediating an increase inblood pressure." (PMID 22121476, 2012). "Our findings showed that HFD-fed rats exhibited a potent increase in serum leptin associated with a significant rise in angiotensin converting enzyme activity (ACE), key enzyme related to hypertension." (PMID 23258993, 2012).
Hypertension (continued). "Hypertension was present in 19 individuals (40%) which required treatment with ACE inhibitors or ARB in 9 (19%), beta-blockers in 10 (21%), diuretics in 8 (17%) and calcium antagonists in 5 subjects (11%)." (PMID 22384011, 2012). "Compared to urban IAPs, rural IAPs prescribed medication with greater frequency, with the exception of ACE inhibitors and beta blockers for prehypertensives as well as ACE inhibitors for stage I hypertension." (PMID 23133546, 2012). "ACE-inhibitory peptides derived from food proteins have attracted particular attention for their ability to prevent hypertension." (PMID 22606330, 2012). "ACE inhibitors or angiotensin receptor blocking agents should be the first choice for controlling hypertension and proteinuria and should be initiated early in the course of the disease." (PMID 23509659, 2012). "ACE inhibitors have been the first line of treatment against hypertension for decades, and their success has served to place ACE and its biologically active product, angiotensin II (Ang II), as central regulators of the renin-angiotensin system (RAS)." (PMID 22121476, 2012). "Treatments by administration of antihypertensive drugs, for example, inhibitors of the angiotensin I-converting enzyme (ACE) aim to reduce blood pressure and lower the risk of hypertension complications." (PMID 21716693, 2012). "Hypertension should be treated aggressively often with multidrug regimen, but pediatricians should be warned against ACE inhibitors until renal artery stenosis has been excluded." (PMID 22290282, 2012). "Individuals with DD genotype, a marker for diabetic nephropathy, hypertension, renal artery stenosis, cardiomyopathies, and coronary and carotid atherosclerosis, have a twofold increase in ACE concentration." (PMID 22144991, 2012). "Forty-five (31.7%) patients were treated for hypertension; 2 (1.3%) with angiotensin converting enzyme (ACE) inhibitors, 29 (19.3%) with angiotensin receptor blockers, 16 (10.7%) with calcium channel blockers." (PMID 22413919, 2012). "94% of the GPs wanted to treat the hypertension, the majority of whom (79%) selected ACE inhibitors as the first choice of treatment." (PMID 22536853, 2012). "Hypertension can be generally treated by negating the effects of angiotensin II through the use of angiotensin-converting enzyme inhibitors (ACE-Is) or angiotensin II type 1 receptor antagonists (ARBs)." (PMID 23097668, 2012). "ACE inhibitors are widely used in the treatment of cardiovascular diseases, including congestive heart failure, coronary artery disease and hypertension." (PMID 23028693, 2012). "70% of GPs wanted to increase hypertension treatment, with ACE inhibitors being the most common choice (55%), followed by thiazides (28%)." (PMID 22536853, 2012). "Due to lack of corresponding research studies in preterm infants, surveys regarding sodium intake reduction and ACE inhibitors implementation as possible alleviating factors of hypertension must be conducted." (PMID 22518177, 2012). "The controversy over the response of African-Americans to angiotensin-converting enzyme (ACE) inhibitors highlights the need to further refine our understanding of the genetic determinants of hypertension and therapeutics." (PMID 22615923, 2012). "For example, in the case of a new angiotensin-converting enzyme (ACE) inhibitor for hypertension, there is both a clear medical need (essential hypertension) and an obvious biological target (inhibitor of the enzyme)." (PMID 23213510, 2012). "Control of hypertension was made with polytherapy, including an antialdosteronic drug and, often, an ACE inhibitor or angiotensin receptor blocker." (PMID 23049641, 2012). "Angiotensin Converting Enzyme Inhibitors (ACE-i) are widely used in the treatment of heart failure and hypertension." (PMID 21276223, 2011). "As hypertension in the context of renal disease is often treated with ACE inhibitors or angiotensin receptor antagonists, some caution is advisable." (PMID 22194875, 2011).
Hypertension (continued). "ACE inhibitors are widely used in clinical practice for the treatment of hypertension, heart failure, myocardial infarction and diabetic nephropathy." (PMID 21810173, 2011). "ACE is the target of ACE inhibitors, a family of drugs used to treat cardiovascular and renal diseases, including hypertension." (PMID 23049672, 2011). "Recently, the Angiotensin Converting Enzyme (ACE) gene also received substantial attention as possible candidate for diabetes, hypertension, cardiovascular disease, and diabetic nephropathy." (PMID 22168210, 2011). "For treatment of her hypertension, we intially used the ACE inhibitor ramipril (2.5 mg daily) and subsequently the angiotensin receptor blocker losartan (12.5 mg daily); her arterial blood pressure declined to the normal range for her age and height." (PMID 21914180, 2011). "About 90% of patients diagnosed to have hypertension were on pharmacologic therapy, the majority of which were taking ACE inhibitors, which abides with the general recommendation." (PMID 22185229, 2011). "Twenty-five (8 females) out of 48 patients (52%) suffered from arterial hypertension and were on diuretics (72%), ACE-inhibitors (52%), Ca-antagonists (36%), beta-blockers (28%) to control the disease." (PMID 22074289, 2011). "In fact, inhibitors of ACE such as Captopril, Enalapril, Lisinopril and Temocapril are widely used in the clinic for the treatment of hypertension." (PMID 22142357, 2011). "For treating hypertension, commonly used drugs include ACE inhibitors, alpha blockers, beta blockers, calcium channel blocker, diuretics, and combination of any of these categories if immediate action is required." (PMID 21731352, 2011). "ACE plays a crucial role in the regulation of blood pressure, and so ACE inhibition is considered to be a useful therapeutic approach in the treatment of hypertension." (PMID 21747748, 2011). "In subjects using ACE inhibitors or ATII receptor blockers for hypertension or other reasons, AF-EEMS was significantly higher than in subjects not using these agents (2.01 ± 0.62 a.u." (PMID 21977038, 2011). "Among processes related to hypertension, angiotensin-I-converting enzyme (ACE) plays an important role in the regulation of blood pressure." (PMID 20479968, 2010). "From the results of univariate analysis, the factors of male gender, diabetes mellitus, hypertension, 4G/4G polymorphism of PAI-1 gene, and DD polymorphism of ACE gene were statistically significant, Cox multivariate analysis was carried out for these factors." (PMID 28352370, 2010). "Anindividualized dialysis prescription is imposed, taking into account the residual renal function andan anti–hypertension treatment, in which the role of the conversion enzyme inhibitors(ACE inhibitor) is intensely debated." (PMID 20302199, 2010). "History of hypertension, heart disease, poorly controlled lung disease, ACE inhibitor or beta-blocker therapy." (PMID 20512278, 2010). "The pharmacological blockade of ACE reduced the hypertrophy secondary to myocardial infarction and hypertension." (PMID 20594303, 2010). "This increase in knowledge has lead to the development of numerous drugs that can help prevent hypertension including angiotensin-converting enzyme (ACE) inhibitors, beta blockers, diuretics, calcium channel blockers and angiotensin II receptor antagonists." (PMID 22319269, 2010). "A large body of data now exists to support the use of angiotensin receptor blockers (ARBs) and ACE inhibitors (ACEIs) in the management of hypertension." (PMID 21994809, 2010). "Captopril is a widely used ACE inhibitor for treatment of arterial hypertension and cardiovascular diseases." (PMID 20462420, 2010). "Angiotensin-converting enzyme (ACE) inhibitors are widely prescribed for patients with diabetes as a nefroprotector drug or to treat hypertension." (PMID 20180980, 2010).
Hypertension (continued). "Captopril is an angiotensin-converting enzyme (ACE) inhibitor widely used in the treatment of arterial hypertension and cardiovascular diseases." (PMID 20462420, 2010). "We report the case of an 84-year-old Caucasian woman with a previous history of arterial hypertension controlled with an angiotensin converting enzyme (ACE) inhibitor." (PMID 21034475, 2010). "The most recent guidelines state that patients with diabetes and albuminuria or hypertension should be treated with an ACE inhibitor or an angiotensin receptor blocker, even when the left ventricular systolic function is normal." (PMID 20525192, 2010). "This is thought to be due in part to the more liberal use of ACE inhibitors to treat Raynaud's phenomenon and hypertension in SSc." (PMID 20936135, 2010). "Although the ACE inhibitor ramipril prevented the development of hypertension in the present study, it also interfered with disease progression, making it highly probable that also sodium and water retention were reduced by ramipril." (PMID 20694143, 2010). "In a previous work, enalapril (another ACE inhibitor) was able to produce an increase in plasma levels of IL-10 in patients with coronary artery disease and arterial hypertension." (PMID 20462420, 2010). "Angiotensin-converting enzyme (ACE) inhibitors are widely prescribed for patients with diabetes as a nephroprotector drug or to treat hypertension." (PMID 20180980, 2010). "Three of the patients had been treated with a calcium antagonist or ACE inhibitor for years, and hypertension developed in the remaining two patients (Patients 1 and 12) during steroid therapy at the time of study." (PMID 20470389, 2010). "Inhibition of ACE is considered to be a useful therapeutic approach in the treatment of hypertension." (PMID 20479968, 2010). "Many studies have been attempted in the synthesis of ACE inhibitors such as captopril, enalapril, alcacepril and lisinopril, which are currently used in the treatment of essential hypertension and heart failure in humans." (PMID 20479968, 2010). "Both angiotensin converting enzyme (ACE) inhibitors and beta blockers are widely used drugs for the treatment of hypertension." (PMID 19471593, 2009). "For example, although CCBs and beta-blockers are the preferred option in CHD patients with hypertension, ACE inhibitors and diuretics were prescribed most frequently." (PMID 20003298, 2009). "Angiotensin-I converting enzyme (ACE) is a significant component of RAS and an insertion/deletion (I/D) polymorphism in its gene has been implicated in predisposition to hypertension." (PMID 20009302, 2009). "Angiotensin-converting enzyme (ACE) inhibitors are drugs with different structures and activities used to treat heart failure and hypertension." (PMID 19508704, 2009). "The administration of ACE inhibitors in the later phases of hypertension in SHR-SP rats also decreased mortality, suggesting that ACE inhibitors reduce cardiovascular risk and atherosclerosis in animals in different stages of cardiovascular disease." (PMID 19390623, 2009). "Hypertension was controlled (145/90 mmHg) by means of ACE-inhibitors (irbesartan 300 mg/day, ramipril 5 mg/day), beta-blockers (carvedilole 25 mg/day) and Ca antagonists (nifedipine 60 mg/day)." (PMID 20062740, 2009). "Aliskiren has the potential to become the first orally active renin inhibitor that provides a true alternative to ACE-inhibitors and Ang II receptor antagonists in therapy for hypertension and other cardiovascular and renal diseases." (PMID 27713228, 2009). "Worldwide, captopril remains an important drug, one of the mainstays of ACE inhibitor therapy for hypertension and for heart failure." (PMID 19287817, 2009). "To avoid stopping the anti-hypertension treatment with ACE-inhibitors we decided to use another LDL-apheresis procedure: the extracorporeal precipitation of LDL-cholesterol induced by heparin in acid pH (HELP System, B. Braun AvitumTM Melsungen Germany)." (PMID 20062740, 2009).
Hypertension (continued). "Captopril demonstrates excellent clinical effectiveness in the treatment of hypertension by inhibiting angiotensin converting enzyme (ACE)." (PMID 20376214, 2009). "In a patient with known AS, paramedics should start respiratory support, but only cautiously administer nitroglycerine, diuretic and, for high blood pressure, angiotensin converting enzyme (ACE) inhibitors." (PMID 20062645, 2009). "In this group the proportion of CAD attributable to the interaction of hypertension and ACE I/D DD was as high as 85%." (PMID 18637188, 2008). "Most prominent is the aggressive treatment of hypertension, especially with ACE inhibitors and more recently, with lipid-lowering statins." (PMID 18937871, 2008). "We found a proportion of CAD attributable to the interaction between hypertension and ACE I/D DD genotype around 30% for the whole population and male subgroup analysis." (PMID 18637188, 2008). "Current guidelines recognise the importance of achieving target BP levels and recommend that all patients with diabetes and hypertension should be treated with a combination of several antihypertensive drugs (one of which should be an ARB or ACE inhibitor)." (PMID 18355239, 2008). "The 655 subject heart failure cohort was 69.2% male, with 47.9% having a history of hypertension, 84.0% receiving ACE inhibitor therapy and 69.6% receiving β-blocker therapy." (PMID 18947427, 2008). "The patient was diagnosed with diffuse scleroderma, treated symptomatically and given ACE inhibitors for hypertension." (PMID 18474117, 2008). "By contrast, many studies have shown that newer antihypertensive agents, such as CCBs, ARBs and ACE inhibitors, provide additional benefits by reducing the incidence of CV events in patients with hypertension." (PMID 18355239, 2008). "These patients were newly diagnosed with coronary artery disease, some of whom were taking vasoactive drugs such as ACE inhibitors and beta adrenoceptor blockers for hypertension prior to study enrolment." (PMID 17977546, 2008). "This included using ACE inhibitors as first line for patients with diabetes who developed hypertension, increased use of aspirin, switching patients to glitazones, and conversion to insulin either directly or by referral to secondary care." (PMID 18205947, 2008). "ACE inhibitors are commonly used to treat congestive heart failure and high blood pressure, but other effects have been reported." (PMID 19061507, 2008). "Demographic and echocardiographic dimensions, systolic and diastolic function in Nigerians with essential hypertension on long term drug therapy with ACE—inhibitors, calcium antagonists or their combination." (PMID 20157363, 2008). "In such cases, other therapeutic options should be considered to avoid potential drug interactions, like using paracetamol to manage osteoarthritis in patients with hypertension being treated with ACE inhibitors." (PMID 17880689, 2007). "The most frequent were interactions involving NSAIDs that were prescribed to patients with hypertension and/or chronic heart failure, and prescriptions of NSAIDs and ACE inhibitors." (PMID 17880689, 2007). "Angiotensin Converting Enzyme (ACE) is the only Chr17 candidate gene investigated in detail for the role in the aetiology of essential hypertension." (PMID 17645789, 2007). "The present study examines how polymorphisms of the insertion/deletion (I/D) ACE and M235T AGT genes account for presence and severity of hypertension, and embeds the data in a meta-analysis of relevant studies." (PMID 15642127, 2005). "Renal crisis can be effectivelymanaged when hypertension is aggressively controlled with angiotensin convertingenzyme (ACE) inhibitors." (PMID 16295521, 2005). "Exclusion criteria were: active smoker, elevated cholesterol, hypertension, age > 65 years, diabetes mellitus, treatment with ACE-inhibitors, or known CAD." (PMID 15857519, 2005).